NRG4 (neuregulin 4)
Diseases named in the same sentence as NRG4 in open-access papers (continued):
Sharing a sentence is not in itself a finding about the gene and the disease.
Impaired glucose tolerance (4 papers, 2018 to 2021). An abnormal resistance to glucose, i.e., a reduction in the ability to maintain glucose levels in the blood stream within normal limits following oral or intravenous administration of glucose. "A recent study demonstrated that Nrg4 mRNA levels in subcutaneous and visceral adipose tissues were significantly lower in patients with impaired glucose tolerance or T2DM than in normal individuals." (PMID 29721105, 2018). "In humans, several studies found that Nrg4 mRNA levels were significantly lower in the subcutaneous and visceral adipose tissues of individuals with impaired glucose tolerance and T2DM." (PMID 29721105, 2018). "In a previous study, SAT and VAT NRG4 was significantly decreased in patients with impaired glucose tolerance (IGT) and T2D, but this study did not evaluate insulin sensitivity." (PMID 30766490, 2019). "Moreover, NRG-4 -/- mice showed reduced adiponectin expression in WAT, reduced insulin sensitivity, impaired glucose tolerance, and a decrease in oxygen consumption without a decline in physical activity." (PMID 32655416, 2020).
lipid metabolism disorders (4 papers, 2019 to 2024). "Neuregulin 4 (Nrg4) is a brown fat-enriched endocrine factor that ameliorates lipid metabolism disorders." (PMID 39541216, 2024).
liver disease (4 papers, 2021 to 2024). "We analysed Nrg4 plasma levels and its association with liver disease severity together with the transcriptional profile of the Nrg4 pathway in liver and visceral adipose tissue (VAT) of NAFLD patients." (PMID 33989346, 2021). "Emerging evidence indicates that the liver and BAT are involved in the interorgan crosstalk via Nrg4, and this may play a role in the pathogenesis of liver diseases." (PMID 39162358, 2024).
acute myocardial infarction (3 papers, 2020 to 2025). Necrosis of the myocardium, as a result of interruption of the blood supply to the area. "Recently, it has been demonstrated that administration of Nrg4 could mitigate the fraction of myocardial infarcts in a mouse model of experimental myocardial ischemia." (PMID 32477429, 2020).
Crohn disease (3 papers, 2016 to 2018). A gastrointestinal disorder characterized by chronic inflammation involving all layers of the intestinal wall, noncaseating granulomas affecting the intestinal wall and regional lymph nodes, and transmural fibrosis. "NRG4 levels in animals with ulcerative colitis (UC) and Crohn’s disease are reduced compared to un-inflamed controls." (PMID 27184920, 2016).
diabetic cardiomyopathy (3 papers, 2022 to 2024). Diabetic cardiomyopathy is a disorder of the heart muscle in people with diabetes. "The results of our study identified, for the first time, the protective effect of Nrg4 on diabetic cardiomyopathy and explored the underlying mechanisms." (PMID 36221104, 2022). "Therefore, we speculated that Nrg4 could attenuate diabetic cardiomyopathy by regulating autophagy and explored the underlying molecular signalling pathway using a type 1 diabetes mouse model." (PMID 36221104, 2022). "One study showed that neuregulin-4 attenuates diabetic cardiomyopathy by regulating autophagy via the AMPK/mTOR." (PMID 38195474, 2024). "Collectively, our study provides new mechanistic insight into the alleviation of diabetic cardiomyopathy through autophagy intervention by Nrg4, a potential pharmacotherapeutic agent." (PMID 36221104, 2022). "Nrg4 alleviated diabetic cardiomyopathy in various aspects: improving cardiac function, ameliorating myocardial pathological abnormalities and interstitial fibrosis, and reducing cardiomyocyte apoptosis." (PMID 36221104, 2022). "Neuregulin-4 attenuates diabetic cardiomyopathy by regulating autophagy via the AMPK/mTOR signalling pathway in type 1 diabetic mice." (PMID 36221104, 2022). "Nrg4 intervention attenuated diabetic cardiomyopathy by promoting autophagy in type 1 diabetic mice." (PMID 36221104, 2022). "Therefore, we demonstrated that Nrg4 treatment alleviated diabetic cardiomyopathy by promoting autophagy." (PMID 36221104, 2022). "Since the disruption of autophagy is essential for diabetic cardiomyopathy, we wondered whether Nrg4 attenuated myocardial injury by regulating autophagy." (PMID 36221104, 2022). "Whether Nrg4 may become a clinically relevant approach for the treatment of diabetic cardiomyopathy needs to be further explored." (PMID 36221104, 2022).
Hepatic fibrosis (3 papers, 2021 to 2024). The presence of excessive fibrous connective tissue in the liver. "Furthermore, plasma Nrg4 levels did not correlate with the hepatic fat fraction (r = -0.028, p = 0.829) and were not significantly different between NAFLD patients with or without hepatic fibrosis (p = 0.087)." (PMID 33989346, 2021).
hepatocellular carcinoma (3 papers, 2023 to 2024). A malignant tumor that arises from hepatocytes. "Also, they demonstrated that NRG4 represses NASH-related hepatocellular carcinoma (HCC) by restraining tumor-prone liver microenvironment." (PMID 39872218, 2024).
inflammatory bowel disease (3 papers, 2018 to 2022). A spectrum of small and large bowel inflammatory diseases of unknown etiology. "NRG-4 expression is suppressed in inflammatory bowel disease, whereas exogenous treatment with this protein blocks enterocyte apoptosis in rodent models of intestinal inflammation and is therefore protective." (PMID 32655416, 2020). "Previous evidence of the anti-inflammatory role of the NRG-4/ErbB4 axis came from studies on inflammatory bowel diseases, such as Crohn’s disease and ulcerative colitis." (PMID 32655416, 2020). "Reduced Nrg4 levels were observed in mice and human samples with inflammatory bowel disease, and Nrg4 treatment blocked inflammatory cytokine-induced apoptosis of colonic epithelial cells both in vivo and in vitro, which demonstrated the potential anti-inflammatory effect of Nrg4-ErbB4 signaling." (PMID 36703934, 2022).
non-alcoholic steatohepatitis (3 papers, 2024 to 2025). "In Nrg4-deficient mice with nonalcoholic steatohepatitis, cell death, inflammation, fibrosis, and liver injury are more serious because Nrg4 can positively regulate ErbB3 and ErbB4 to repress the ubiquitination and proteasomal degradation of c-FLIPL to reduce cell death." (PMID 39220365, 2024). "In rodents, Nrg4 inhibits de novo hepatic lipogenesis which in turn suppresses the progression of NAFLD to non-alcoholic steatohepatitis." (PMID 39162358, 2024).
prostate carcinoma (3 papers, 2017 to 2025). A carcinoma that arises from epithelial cells of the prostate gland. "NRG4 has been studied in breast and prostate cancers and has been reported to be associated with poor prognosis." (PMID 37174100, 2023).
bladder cancer (2 papers, 2004 to 2014). "In patients with bladder cancer, the combined HER4/NRG4 signaling unit can be growth inhibitory, and the co-expression of HER4 together with NRG4 is highly correlated to better survival if the two proteins act together rather than individually." (PMID 24728052, 2014).
Chronic colitis (2 papers, 2017 to 2021). A chronic inflammatory disease of the large intestine (colon, cecum and rectum). "This study extends these findings to identify the specific role of acute NRG4/ErbB4 signaling in macrophages and the impact that loss of ErbB4 in macrophages has on acute and chronic colitis." (PMID 33826403, 2021). "Future studies to identify the key cellular source of NRG4 in the colon and how its expression is regulated will provide insight into a possible mechanism underlying chronic colitis." (PMID 28230865, 2017).
complication (2 papers, 2020 to 2024). Any disease or disorder that occurs during the course of, or because of, another disease, treatment, or procedure. "The purpose of our study was to investigate the association of circulating Nrg4 with DPN and 25-hydroxy vitamin D [25(OH)D], a multifunctional secosteroid hormone that regulates other neurotrophic factors and adipokines gene expression, and other diabetic vascular complications." (PMID 32477429, 2020).
fibrosis (2 papers, 2021 to 2022). the formation of excess fibrous connective tissue in an organ or tissue in a reparative or reactive process. "Therefore, we investigated the expression of 82 genes of the Nrg4 related ErbB signalling pathway in the liver of obese patients without NAFLD, NAFL and NASH patients without fibrosis." (PMID 33989346, 2021).
glioma (2 papers, 2019 to 2021). A benign or malignant brain and spinal cord tumor that arises from glial cells (astrocytes, oligodendrocytes, ependymal cells). "The results showed that NRG1 (p=0.0045), NRG3 (p=0.0073) and NRG4 (p=0.026) were significantly related to survival in recurrent gliomas (all WHO grade), and NRG2 (p=0.031) and NRG3 (p<0.0001) were significantly related to survival in primary gliomas (all WHO grades)." (PMID 34054873, 2021).
hyperglycaemia (2 papers, 2016 to 2017). "In contrast, our data demonstrate that circulating Nrg4 is significantly decreased in individuals with hyperglycaemia compared to their controls and inversely associated with fasting glucose in more than 1000 obese adults." (PMID 27772531, 2016).
hyperthyroidism (2 papers, 2020 to 2025). Overactivity of the thyroid gland resulting in overproduction of thyroid hormone and increased metabolic rate. "The SVM-CNN+LSTM multimodal model, which integrates serum NRG4 levels with ultrasound features, significantly enhances the predictive accuracy of hyperthyroidism in T2DM patients." (PMID 40740865, 2025).
insulinoma (2 papers, 2013 to 2022). "NRG-4 has been reported to regulate the lineage determination of islet cells during pancreatic development, as well as to increase DNA synthesis in rat insulinoma cells." (PMID 24348587, 2013). "Nrg4 was similarly shown to be the most insulin-stimulating of the Nrg family in a rat insulinoma cell line in a subsequent study, suggesting that Nrg4 may have a potent role in regulating islet cell growth and secretion." (PMID 36703934, 2022).
liver cancer (2 papers, 2023 to 2024). An epithelial or non-epithelial malignant neoplasm that arises from the liver. "We recently demonstrated that recombinant human NRG4-Fc (hNRG4-Fc) fusion protein suppresses the development of NASH-associated liver cancer." (PMID 38015639, 2024). "Recent work has demonstrated that NRG4 signaling serves as a checkpoint for NASH progression and the development of NASH-associated liver cancer." (PMID 38015639, 2024). "Neuregulin 4 (Nrg4) is a fat-derived hormone that protects mice from nonalcoholic steatohepatitis (NASH) and NASH-associated liver cancer by shaping hepatic lipid metabolism and the liver immune microenvironment." (PMID 38015639, 2024). "Both ERBB2 and NRG4 correlated with the Barcelona Clinic Liver Cancer stage, ERBB2 correlated with the tumor-maximal diameter, and NRG4 correlated with a tumor number." (PMID 37174100, 2023). "Furthermore, NRG4 reprograms the liver immune microenvironment and inhibits the development of NASH-related liver cancer." (PMID 38015639, 2024).
polycystic ovary syndrome (2 papers, 2021 to 2022). A disorder that manifests as multiple cysts on the ovaries. "However, there have been few reports on serum levels of anti-mullerian hormone, irisin, NRG4, and interventions for weight loss in obese adolescent girls with polycystic ovary syndrome at home and abroad." (PMID 34427289, 2021). "The study is aimed at investigating the association of serum irisin, neuregulin 4 (NRG4), and anti-müllerian hormone (AMH) with adolescent obesity with polycystic ovary syndrome (PCOS) and the efficacy of weight management interventions." (PMID 34427289, 2021).
schizophrenia (2 papers, 2007 to 2018). A major psychotic disorder characterized by abnormalities in the perception or expression of reality. "Neuregulins, with the exception of neuregulin-4 (NRG4), have been shown to be extensively involved in many aspects of neural development and function and are implicated in several neurological disorders, including schizophrenia, depression and bipolar disorder." (PMID 29317193, 2018).
acromegaly (1 paper, 2023). Acromegaly is an acquired disorder related to excessive production of growth hormone (GH) and characterized by progressive somatic disfigurement (mainly involving the face and extremities) and systemic manifestations. "Taken together, the association between neuregulin-4 and body fat distribution in acromegaly deserves further research." (PMID 37373801, 2023). "In the acromegaly group, lean body mass (r = 0.347, p = 0.033), fasting glucose (r = 0.402, p = 0.010), TG (r = 0.480, p = 0.002) and TyG index (r = 0.547, p < 0.001) were positively associated with neuregulin-4." (PMID 37373801, 2023). "Serum neuregulin-4 levels are higher in female patients with acromegaly and appear to be associated with some metabolic components, suggesting that it might be a protective factor in acromegaly." (PMID 37373801, 2023). "As the cause of increase in circulating neuregulin-4 in acromegaly, one can speculate that increased ectopic intramuscular adipose tissue may be the source of neuregulin-4." (PMID 37373801, 2023). "In light of this information, exploring the neuregulin-4 level, which is closely associated with the modulation of glucose and lipid metabolism, may be important regarding hormonal control and metabolic changes in patients with acromegaly." (PMID 37373801, 2023). "Neuregulin-4 correlated positively with fasting glucose, triglyceride (TG), triglyceride/glucose (TyG) index, and lean body mass in the acromegaly group." (PMID 37373801, 2023). "In this study, we aimed to investigate LTL and neuregulin-4 levels in female patients with acromegaly and compare them with healthy controls." (PMID 37373801, 2023). "The study aimed to examine leukocyte telomere length (LTL) and serum neuregulin-4 levels and their relationship with disease activity, co-morbidities and body fat distribution in female acromegaly patients." (PMID 37373801, 2023). "In the present study, neuregulin-4 levels were found to be higher in female patients with acromegaly than controls." (PMID 37373801, 2023). "Our findings indicate that acromegaly is associated with unchanged LTL and high neuregulin-4 levels in female patients." (PMID 37373801, 2023). "In the separate analysis, both acromegaly and control groups showed a positive correlation between neuregulin-4 and fasting glucose." (PMID 37373801, 2023). "Lean body mass and neuregulin-4 levels were significantly higher in our acromegaly group than in the control group." (PMID 37373801, 2023). "A positive correlation was observed between neuregulin-4 and TG in the acromegaly group, similar to the whole group analysis." (PMID 37373801, 2023). "However, median neuregulin-4 levels were significantly higher in the acromegaly group than the control group (1.06 vs. 0.79 ng/mL, p = 0.037)." (PMID 37373801, 2023). "Considering the reported associations between neuregulin-4 and glucose metabolism and the positive correlation with fasting glucose found in the present study, it is difficult to say that increased neuregulin-4 level in the acromegaly group is due to the acromegaly itself." (PMID 37373801, 2023). "However, the relationship between acromegaly, the aging process, and neuregulin-4 involves complex mechanisms, and further studies are needed." (PMID 37373801, 2023). "However, serum neuregulin-4 was significantly higher in patients with acromegaly than those in the control group (p = 0.037)." (PMID 37373801, 2023). "Neuregulin-4 was positively correlated with lean body mass in the acromegaly group in our study." (PMID 37373801, 2023). "We think that co-morbid conditions, which are frequently seen in acromegaly, may have a confounding effect on this association between LTL and neuregulin-4." (PMID 37373801, 2023). "Taken together, an increase in neuregulin-4, a batokine responsible for the regulation of glucose, lipid and energy homeostasis, might be a reactive response to increased glucose and lipid levels in acromegaly." (PMID 37373801, 2023).
acromegaly (continued). "As far as we know, there is no study regarding this relationship between acromegaly and neuregulin-4 in the literature." (PMID 37373801, 2023). "In our study, we found a negative correlation between LTL and neuregulin-4, which is a peptide from the growth factor family, in the control group, but not in the acromegaly group." (PMID 37373801, 2023). "Therefore, a question may arise that elevated neuregulin-4 levels may not result from acromegaly directly, but it is difficult to separate them." (PMID 37373801, 2023).
Anxiety (1 paper, 2021). Intense feelings of nervousness, tension, or panic often arise in response to interpersonal stresses. "Importantly, the morphologic defects caused by the loss of NRG4 caused an impairment in the motor skills of adult mice, while total motor activity, anxiety and response to novelty were unaffected." (PMID 33495243, 2021).
cardiac hypertrophy (1 paper, 2022). "Nrg4 treatment significantly prevented the development of cardiac hypertrophy and cardiac dysfunction in type 1 diabetic mice." (PMID 36221104, 2022).
cardiomyopathy (1 paper, 2025). A disease of the heart muscle or myocardium proper. "Neuregulin-4 (Nrg4), an adipokine, has been shown to ameliorate autophagy dysfunction in T1DM cardiomyopathy by activating AMPK phosphorylation, thus enhancing autophagosome formation." (PMID 40004130, 2025).
colorectal cancer (1 paper, 2025). A primary or metastatic malignant neoplasm that affects the colon or rectum. "We systematically analyzed the prognostic value of transcription levels of SFs in colorectal cancer (CRC) and found that RAB3A interacting protein (RAB3IP), programmed cell death 4 (PDCD4), golgin B1 (GOLGB1), and neuregulin 4 (NRG4) as the most predictive markers for the prognosis of CRC." (PMID 40657366, 2025).
coronary stenosis (1 paper, 2020). Narrowing of the coronary artery lumen diameter. "Number of vessels with coronary stenosis in all patients containing SAP and ACS were compared in Nrg4 quartiles." (PMID 32242042, 2020).
diabetic polyneuropathy (1 paper, 2025). "Nrg4 plays an important role in metabolic processes and is associated with various diseases, including diabetic polyneuropathy." (PMID 40137134, 2025). "These factors contribute to the development of diabetic polyneuropathy, suggesting that Nrg4 plays a critical role in its development." (PMID 40137134, 2025).
gastric cancer (1 paper, 2014). A primary or metastatic malignant neoplasm involving the stomach. "This demonstrates that both HER4 and its specific ligand NRG4 are down-regulated in gastric cancer." (PMID 24728052, 2014).
heart failure (1 paper, 2025). Inability of the heart to pump blood at an adequate rate to meet tissue metabolic requirements. "The results thus far concerning Nrg4 have been promising in identifying a protective batokine limiting myocardial remodelling and heart failure, although substantial future work is required to fully delineate the role of Nrg4 in the heart failure process." (PMID 41515891, 2025).
lipodystrophy (1 paper, 2025). A congenital or acquired disorder characterized by abnormal loss or redistribution of the adipose tissue in the body. "Together, our data indicate that NRG4's beneficial effects may depend on the presence of functional AT, which is profoundly impaired in lipodystrophy." (PMID 40580113, 2025).
liver cirrhosis (1 paper, 2023). "Recently, the incidence of liver cirrhosis and HCC related to NASH has increased, and examining the role of NRG4 in the development and progression of HCC-related NASH is necessary." (PMID 37174100, 2023). "Since our study focused on the prognosis of HCC, controls such as healthy controls, chronic viral hepatitis B, or liver cirrhosis were not included, and the predictive performance of our marker using ERBB2, NRG4, and MIG6 for the diagnosis of HCC could not be confirmed." (PMID 37174100, 2023).